EGFR (epidermal growth factor receptor)
Diseases named in the same sentence as EGFR in open-access papers (continued):
Sharing a sentence is not in itself a finding about the gene and the disease.
tumor (continued). "In conclusion, tumour islet macrophage infiltration was identified as a strong favourable independent prognostic marker for survival but not correlated with the molecular changes of the EGFR in patients with resected NSCLC." (PMID 18283317, 2008). "However, in our series we identified a group of 29 tumours with intense cortactin expression in which the EGFR was not overexpressed." (PMID 18268492, 2008). "In these tumours, intense cortactin staining occurred in the absence of strong EGFR staining." (PMID 18268492, 2008). "In addition, our findings have identified a subgroup of VEGF-positive and EGFR-negative tumours, which are more resistant to radiotherapy and should perhaps be considered candidates for innovative neoadjuvant combined modalities." (PMID 18182986, 2008). "However, imaging approaches affording early identification of tumor response in EGFR-dependent carcinomas have so far been lacking." (PMID 19079597, 2008). "This may be the case for the subset of cortactin-overexpressing/EGFR-nonoverexpressing tumours that we describe in which activation or overexpression of signalling components downstream of the receptor could influence cell survival and growth." (PMID 18268492, 2008). "However, its fast degradation in vivo in combination with low tumor activity uptake levels along with pronounced activity concentration in the liver, kidney and intestine, obtained in tumor-bearing rat biodistribution studies, rendered [11C]-ML03 ineffective as a tracer for imaging of the EGFR." (PMID 18991714, 2008). "A negative influence of EGFR targeting on angiogenic biochemical mediators has been shown for both mAbs and TKIs; for instance, the tumour labelling in VEGF (vascular endothelial growth factor) and factor VIII was reduced in xenograft models by C225 as well as by ZD1839." (PMID 18506149, 2008). "Thus, EGFR content in EGFR-positive/pEGFR-negative tumours does not reflect the level of receptor activation." (PMID 18522728, 2008). "The tumours (n = 4) displaying high polysomy for EGFR all stained negative for HER2-neu." (PMID 18182111, 2008). "Interestingly, none of the tumour specimens with low cortactin levels (cortactin nonoverexpressors) overexpressed the EGFR." (PMID 18268492, 2008). "In addition, two PR were seen in nine patients with EGFR-negative tumours enrolled in a phase II study of single agent cetuximab." (PMID 17940504, 2007). "More controversial is whether elevated serum HER2 and/or serum EGFR levels might be used to select patients for targeted therapies, even if the primary tumour tissue did not over-express these oncogenes." (PMID 17976236, 2007). "HER2 amplification in the absence of EGFR amplification was seen in three additional tumours." (PMID 17626639, 2007). "Although there is no previous report describing the clinical application of cetuximab to oesophageal SCC patients, it has been shown that cetuximab-induced antitumour activity did not correlate directly with the levels of EGFR expression in human tumour xenograft models." (PMID 17622245, 2007). "This existing knowledge suggests that HIF-1α may be a good indicator of tumor response to EGFR-targeted therapy, but to date no studies have investigated this possibility." (PMID 17931419, 2007). "Among 47 (48%) EGFR-negative primary tumours, 35 cases (74%) expressed phosphorylated Akt and MAPK." (PMID 17579627, 2007). "Tyrosine kinase inhibitors effectively prevent autophosphorylation of EGFR and HER2 in these tumour cells; however, the transphosphorylation of HER3 is only transiently suppressed and HER3 ultimately escapes inhibition by TKIs in HER2-overexpressing tumour cells." (PMID 17667926, 2007).
tumor (continued). "Finally, IHC data for EGFR and/or ErbB2 overexpression were correlated with tumour phenotype (IBC/non-IBC), ER status and the presence of transcriptionally active NF-κB dimers." (PMID 17700572, 2007). "The second factor is related to possible nonuniform EGFr expression within the tumour area." (PMID 17088913, 2006). "However, the potential changes in the tumor's EGFR status due to postoperative chemotherapy effects have not been addressed." (PMID 17163999, 2006). "Experience with monoclonal antibodies against nontumour-specific antigens such as CD20 and EGFR suggests that the enhanced expression of TfR on tumour cells and the targeting effect of Tf–Hp may provide an effective therapeutic window." (PMID 16819545, 2006). "Many patients whose tumours express EGFR fail to respond to EGFR targeted therapy, and conversely, patients who respond may have tumours that do not exhibit EGFR expression." (PMID 16622439, 2006). "Most of the tumours with amplification of TOP2A show neither expression of CK5/6 nor EGFR, only in two TOP2A-amplified samples expression of CK5/6 or EGFR could be detected." (PMID 17088909, 2006). "In addition to its antiangiogenic properties, ZD6474 also has activity against the epidermal growth factor receptor (EGFR) tyrosine kinase, which could impart a direct inhibitory effect on tumour cell growth and survival." (PMID 15928657, 2005). "Two of the tumours without increased LRIG1 copy number also had lowered EGFR expression." (PMID 16168117, 2005). "We did not assess the predictive value of EGFR on tumor response after preoperative treatment." (PMID 15967033, 2005). "The prediction from this in the clinical situation is that while some tumours expressing high levels of EGFR will respond well to EGFR inhibitors, others may not." (PMID 15280923, 2004). "Several possible explanations have been put forth to explain the failure to demonstrate a benefit: inadequate dosing, reduced drug delivery to tumour, lack of sustained potency and failure to select patients on the basis of having tumours in which EGFR presents a growth advantage." (PMID 15365562, 2004). "In this study, EGFR expression was significantly associated with features recognised to reflect poor prognosis, including high (poor) histological grade, high NPI score, negative ER status, larger tumour size, the development of distant metastases and death." (PMID 15480434, 2004). "EGFR-TK inhibition has not yet been evaluated in the antineoplastic treatment of NE tumours." (PMID 14583782, 2003). "Thus, the recurrence rate of TCCs with increased EGFR and/or c-erbB-2 expression was significantly higher than that of tumours showing no increased expression of these receptors (P < 0.01)." (PMID 7819052, 1995). "Since patients with EGFr+ tumours are unlikely to respond to hormone therapy it may be possible to select them for trials of systemic adjuvant chemotherapy." (PMID 1846551, 1991). "Hence, while EGFR alterations are valuable for molecular classification and targeted therapy stratification, serum EGFR concentration alone is not reliable indicators of tumor dynamics." (PMID 41399659, 2026). "No predictive trends were seen for PD‐L1 tumor proportion score or CPS, EGFR expression or mutation status, tumor mutational burden, or microsatellite instability (data not shown); however, there was a significant reduction in EGFR expression across patients following ASP‐1929 photoimmunotherapy." (PMID 40852760, 2026). "Additionally, our findings suggest that the efficacy of EGFR-TKIs and ICIs therapy may not depend on detecting a singular tumor feature or cell type." (PMID 39833943, 2025).
tumor (continued). "Furthermore, EGFR is generally not considered a relevant therapeutic target in this tumor type." (PMID 41516067, 2025). "Furthermore, mIHC analysis confirmed that AREG and EGFR/ERBB2, as well as NAMPT and ITGA5/ITGB1, were overexpressed in the PMC_P region, verified in clinical specimen suggesting that these LRPs play a critical role in mediating tumor initiation in the tipping point." (PMID 40976783, 2025). "However, traditional ADCs that target receptors expressed on both tumor cells and certain non-malignant tissues (such as EGFR and TROP2) are often associated with unavoidable on-target off-tumor toxicities, leading to dose reductions or treatment discontinuation." (PMID 40057807, 2025). "Furthermore, due to the high expression of epidermal growth factor receptors (EGFR) on TNBC cell membranes, modifying epidermal growth factor-peptides (EGF_Peptides) is considered an effective strategy to improve the targeting efficiency of biomimetic nanodrug delivery system to the tumor sites." (PMID 39906202, 2025). "Furthermore, certain tumor-specific markers such as HER2 or EGFR may not be present in CTCs due to tumor heterogeneity, early dissemination, epigenetic changes, and/or drug-induced selection events." (PMID 40867346, 2025). "Mechanistically, PD-L1 expression should not be interpreted analogously to oncogenic target detection (as for HER2 or EGFR), since the therapeutic action of anti-PD-1/PD-L1 antibodies occurs primarily at the immune synapse rather than through direct elimination of PD-L1-positive tumor cells." (PMID 41425548, 2025). "Notably, these mutations can sustain oncogenic signaling and confer resistance to EGFR-targeted therapies, while ERBB2 amplification is linked to a non-inflammatory tumor microenvironment that may impact immunotherapy response." (PMID 40828885, 2025). "However, in the case of EGFR as a vector target, transduction into non-target tissues and the low availability of the receptor in tumor tissues prevented effective tumor transduction by affilin-decorated vectors, making EGFR a difficult receptor to target with adenoviral vectors." (PMID 40697381, 2025). "In addition, IL-6 interacts with both epidermal growth factor receptor (EGFR) to promote immunosuppressive microenvironment by inducing myeloid-derived suppressor cells (MDSC) and the vascular endothelial growth factor receptor (VEGFR) to drive tumor-induced angiogenesis in EC." (PMID 40519900, 2025). "Moreover, EGFR-mutant LUAD typically exhibits a “cold” immune phenotype and shows limited response to immune checkpoint inhibitors (ICIs), suggesting that this subtype possesses distinct features in terms of tumor microenvironment (TME), immune escape mechanisms, and gene expression profiles." (PMID 41164195, 2025). "Therefore, it is possible that the USP8 P681Q mutation could impact ACTH processing or secretion in corticotroph tumor cells, without any actions on the EGFR pathway." (PMID 40544420, 2025). "PD-L1 expression, TMB, and gene alterations were assessed in 50 tumour samples from patients with metastatic NSCLC, obtained at the time of diagnosis, prior to therapy, previously tested according to a standard clinical protocol by PCR, and negative for EGFR mutation." (PMID 40650126, 2025). "Moreover, the increased EGFR protein levels in the tumour tissues of NSCLC patients and the decreased EGFR protein levels in xenograft tumours following EPN3 knockdown suggest that the ErbB signalling pathway may play a role in A549 cell proliferation and differentiation after EPN3 knockdown." (PMID 39910656, 2025). "Moreover, DPP4 levels were markedly increased in the subcutaneous tumor tissues post‐treatment, which simulated the minimal residual disease (MRD), as well as in the orthotopic tumors receiving osimertinib and residual lesions from patients after EGFR‐TKIs treatment." (PMID 40479551, 2025).
tumor (continued). "Furthermore, EGFRm circulating tumor DNA (ct-DNA) clearance on treatment (around cycle 3/4) predicted longer PFS in patients with detectable baseline ctDNA, while nearly half of the patients developed acquired resistance, mainly involving MET, EGFR, and KRAS alterations." (PMID 40725428, 2025). "Interestingly, TDEs in oral cancer can also transfer oncogenic EGFR from tumor cells to endothelial cells, thus increasing the expression of vascular endothelial growth factor (VEGF); this can support invasiveness and metastasis, thus promoting neovascularization and tumor niche formation." (PMID 40723410, 2025). "Since invalid cobas tests with a low IC Ct value were attributed to EGFR amplification rather than low tumor content or poor DNA quality, we hypothesized that it might be feasible to use diluted DNA samples (from 2 ng/μL to 1 ng/μL) for the second round of cobas EGFR testing." (PMID 40310364, 2025). "Finally, although tumor sidedness was evaluated, the findings could not be fully contextualized with existing evidence that EGFR inhibitors benefit left-sided RAS-WT tumors, owing to limited data, representing an important interpretative limitation." (PMID 41458799, 2025). "This suggests that a patient population otherwise not being considered for EGFR-targeting tyrosine kinase inhibitors in a front-line setting due to lack of mutations detected by sequencing, may benefit from such a therapy if BACE1 is present in their tumor." (PMID 40601773, 2025). "Furthermore, an intersection analysis of the PamChip phosphorylation data with the gene expression results identified EGFR, MET, and FAK as the sole genes exhibiting upregulated expression at both the transcript and protein phosphorylation levels across the two TKI-resistant tumor cell line models." (PMID 41281943, 2025). "Among these cases, we excluded those without data on RAS status, tumor sidedness, or target lesion measurements; those whose tumor evaluations were not performed at 8 ± 2 weeks; and where the participants were treated with an anti-EGFR antibody plus bevacizumab." (PMID 40280867, 2025). "This is in contrast to our observations where HER2 amplification is associated with an inflammatory phenotype characterised by activation of the cGAS-STING pathway and we observe that HER2/EGFR blockade may be immunosuppressive rather than increasing tumour immune cell populations." (PMID 39395265, 2024). "However, tumor tissues are not exclusive in their co-expression of EGFR and HER2." (PMID 38650005, 2024). "However, there are still some patients who do not respond to anti-EGFR monoclonal antibodies or develop secondary resistance, which may be related to the activation of other signaling pathways in the tumor." (PMID 39555098, 2024). "Additionally, considering the expanding clinical applications of tumor immunology, our review offers a more comprehensive understanding of the correlation between CMTM family and immunity, encompassing various mechanisms, including PD-L1/PD-1, EGFR, WNT, and JAK2/STAT3 pathways." (PMID 38223763, 2024). "Interestingly, targeted ANC@RNP/crEGFR‐PLK1 therapy resulted in significant tumor growth reduction when compared to single gene editing counterparts (ANC@RNP/crEGFR or ANC@RNP/crPLK1), indicating the synergistic role of dual EGFR and PLK1 inhibition in tumor progression." (PMID 38943253, 2024). "Tumor infiltration by CD8 T cells was not assessed in our study, which could have been of interest as it has been described to predict survival after immune checkpoint inhibitor treatment in EGFR-mutated NSCLC." (PMID 39509381, 2024). "Moreover, the 5-year results from the phase III NCT02220894 study highlighted the sustained efficacy of pembrolizumab as a first-line treatment for locally advanced or metastatic NSCLC without EGFR or ALK alterations in all PD-L1 tumor proportion score (TPS) groups compared to chemotherapy." (PMID 39199653, 2024).
tumor (continued). "Moreover, compared to the LCO group, CAF-targeting treatment did not significantly enhance the sensitivity of EGFR-mutated LC23 tumor cells in LCAs to osimertinib, further suggesting little protection of LC23 CAFs for the corresponding tumor cells." (PMID 38643164, 2024). "Notably, an in vivo study suggested that USP25/28 inhibitor showed a potent anti-tumor effect on pancreatic cell-derived xenograft (CDX) mouse model, implying combining DUB inhibitors with EGFR inhibitors or chemotherapeutic agents may enhance therapeutic efficacy." (PMID 39048965, 2024). "However, EGFR-mutated NSCLC may be at a disadvantage for immunotherapy because of the lack of smoking history and low tumor mutation burden (TMB)." (PMID 39280252, 2024). "This ADC contrasts with other conjugates with moderate or unknown mAb biological activity, such as D2B–duocarmycin, intended for prostate cancer, and CyEt-Pan-Duo, targeting EGFR, showing no tumor growth inhibition and growth inhibition without tumor-shrinking, respectively." (PMID 39409913, 2024). "Also, the vandetanib administration reduced tumors but could not induce tumor regression in models not expressing EGFR or RET." (PMID 38892472, 2024). "Whole exome sequencing (WES) was performed on pretreatment tumor tissue with matched normal samples from NSCLC patients with (n = 25, detected in tissue or blood rebiopsies) or without (n = 14, negative tissue rebiopsies only) subsequent EGFR p.T790M mutation after treatment with 1G/2G EGFR TKI." (PMID 38284983, 2024). "Additionally, the EGFR/PI3K/AKT/mTOR pathway directs macrophage polarization towards the M2 phenotype, which secretes growth factors such as EGF, platelet-derived growth factor (PDGF), and transforming growth factor (TGF)-β, favoring tumor cell proliferation and survival." (PMID 38191508, 2024). "Thus, a liquid biopsy-guided approach at progression in elderly patients with reduced PS and reduced tolerability for tumor rebiopsies may offer feasible and effective therapy guidance, as in this case where it disclosed the option of combining ALK- and EGFR-TKI." (PMID 37685884, 2023). "Patients who carried driver gene mutations (EGFR or BRAF mutations or ALK/ROS1 rearrangements), who received ICIs as neoadjuvant treatment or less than two cycles of ICIs, who were lost to follow-up, and who did not complete the tumor response assessment were excluded from the study." (PMID 37359565, 2023). "However, the subgroups of patients with CRC stratified by sex and subsequent tumor location had distinctive molecular patterns of PD-L1 expression, MMR/MSI status, and EGFR expression, which could have a potential predictive role in patient screening for combination therapies." (PMID 36802389, 2023). "Indeed, compared to the WT, EGFR mutant cancer cells downregulate the expression of CXCL10, chemoattractant for CD8 T cells, and CCL21, important for the accumulation of NK cells and naïve T cells, and whole tumor extracts revealed a trend toward a lower expression levels of IFNγ." (PMID 37180110, 2023). "Considering that CEA reflects the tumor burden in mCRC6, we speculate that an increased CEA response may be a reflection of tumor shrinkage and a greater depth of response (DpR) in patients receiving an anti-EGFR mAb regimen than in those receiving an anti-VEGF mAb treatment." (PMID 37185297, 2023). "Indeed, in vivo studies of gefitinib have shown that although there was an effect on dephosphorylating EGFR in amplified tumours, there was no demonstrable effect on EGFR pathway activity, highlighting mechanisms for resistance that are independent of direct EGFR pathway activation." (PMID 36765632, 2023).